MPLKIP (M-phase specific PLK1 interacting protein)
Description:
May play a role in maintenance of cell cycle integrity by regulating mitosis or cytokinesis.
Synonyms: C7orf11; TTDN1; ORF20; ABHS; TTD4
Tractability: PROTAC: its protein half-life has been measured.
Gene: Protein-coding gene on chromosome 7 (40,126,027 to 40,134,622, reverse strand). Ensembl gene ENSG00000168303.
Subcellular location: Nucleus; Cytoplasm; Cytoplasm, cytoskeleton, microtubule organizing center, centrosome
Subcellular location (Human Protein Atlas): Nucleoplasm; Golgi apparatus; Vesicles
Gene Ontology:
Molecular function: protein binding
Cellular component: centrosome; cytoplasm; midbody; nucleoplasm; nucleus
Genetic constraint (gnomAD): Loss-of-function variants: 16 observed, 12.7 expected, observed/expected ratio (o/e) 1.26, 90% interval 0.85 to 1.82. The synonymous counts are far from expectation, so gnomAD's model fits this gene poorly and the ratio says little. Missense variants: 282 observed, 205.11 expected, observed/expected ratio (o/e) 1.37, 90% interval 1.25 to 1.52. Synonymous variants: 126 observed, 82.09 expected, observed/expected ratio (o/e) 1.53, 90% interval 1.33 to 1.78.
Homologues: Orthologues: chimpanzee MPLKIP (100% identical), macaque MPLKIP (99% identical), rabbit MPLKIP (95% identical), dog MPLKIP (94% identical), guinea pig MPLKIP (93% identical), pig MPLKIP (92% identical), rat Mplkip (89% identical), mouse Mplkip (88% identical), mouse Mplkipl1 (82% identical), zebrafish mplkip (40% identical), tropical clawed frog gs17 (28% identical).
Diseases named in the same sentence as MPLKIP in open-access papers:
MPLKIP is named in the same sentence as 23 diseases in open-access papers, as found by Europe PMC text mining. Sharing a sentence is not in itself a finding about the gene and the disease. The quoted sentences say what the papers report.
trichothiodystrophy (4 papers, 2016 to 2023). Trichothiodystrophy or TTD is a heterogeneous group disorders characterized by short, brittle hair with low-sulphur content (due to an abnormal synthesis of the sulfur containing keratins). "MPLKIP‐deficiency is one of the causative genes for trichothiodystrophy (TTD), a condition characterized by clinical features associated with ectodermal abnormalities." (PMID 37800682, 2023). "To summarize, the homozygous G insertion (rs747470385) in her MPLKIP gene caused trichothiodystrophy nonphotosensitive 1 (TTDN1) with hypergonadotropic hypogonadism." (PMID 30598092, 2018).
hypogonadism (2 papers, 2018 to 2023). A disorder characterized by decreased function of the gonads. "Although the relationship between hypogonadism and the MPLKIP gene mutation is unclear, the gene plays a key role in regulating in cytokinesis and mitosis that may be a possible reason to explain the relationship." (PMID 30598092, 2018).
cardiomyopathy (1 paper, 2016). A disease of the heart muscle or myocardium proper. "Overall our study expands the allelic and phenotypic spectra of MPLKIP-related TTDN, to include a splice variant that causes cardiomyopathy as part of the TTDN phenotype." (PMID 26880286, 2016). "This study extends the allelic and phenotypic spectra of MPLKIP-related TTDN, to include a splice variant that causes cardiomyopathy as part of the TTDN phenotype." (PMID 26880286, 2016). "Notably all affected individuals from the Pakistani families have mitral regurgitation which is probably due to cardiomyopathy, a feature that has not been reported as part of the TTDN spectrum specifically caused by MPLKIP mutations." (PMID 26880286, 2016).
Hypergonadotropic hypogonadism (1 paper, 2018). Reduced function of the gonads (testes in males or ovaries in females) associated with excess pituitary gonadotropin secretion and resulting in delayed sexual development and growth delay. "Our results indicate that the homozygotic G insertion in MPLKIP results in the TTDN1 with hypergonadotropic hypogonadism, while heterozygous carriers of the same mutation have no symptoms and healthy." (PMID 30598092, 2018).
Intellectual disability (1 paper, 2016). "The TTDN features identified in the three Pakistani families reported here overlapped with clinical findings in MPLKIP variant carriers with TTDN, particularly for hair abnormalities, intellectual disability and susceptibility to infections." (PMID 26880286, 2016).
keratosis pilaris (1 paper, 2023). A form of dry skin characterized by hair follicles plugged by scale. "The MPLKIP‐deficient subjects in this study all presented ectodermal abnormalities, including keratosis pilaris, dry skin, and hyperkeratotic plaques on the scalp." (PMID 37800682, 2023). "MPLKIP‐deficient individuals also display characteristic skin abnormalities such as dry skin and keratosis pilaris, and suffer from recurrent infections, including gastrointestinal infections, sinopulmonary infections, otitis media, and sepsis." (PMID 37800682, 2023).
Mitral regurgitation (1 paper, 2016). An abnormality of the mitral valve characterized by insufficiency or incompetence of the mitral valve resulting in retrograde leaking of blood through the mitral valve upon ventricular contraction. "Additionally mitral regurgitation was identified in all affected individuals, expanding the TTDN1 spectrum caused by MPLKIP variants." (PMID 26880286, 2016).
renal failure (1 paper, 2018). "277delT results in seizure disorders, and mutation c.505dupA within the MPLKIP gene has been shown to cause severe renal failure." (PMID 30598092, 2018).
cancer (1 paper, 2016). A tumor composed of atypical neoplastic, often pleomorphic cells that invade other tissues. "On the other hand, MPLKIP is expressed in fetal skin and fibroblasts, while PLK1 expression is highest in tissues with actively proliferating cells (e.g. gonads, cancers)." (PMID 26880286, 2016).
MPLKIP also shares sentences with these, for which no sentence is quoted: infection (7 papers); Bardet-Biedl syndrome (1); diaphanospondylodysostosis (1); Ehlers-Danlos syndrome (1); gonad disorder (1); HCMV infection (1); herpes zoster (1); microcephaly (1); osteoporosis (1); primary ciliary dyskinesia (1); Pyle disease (1); seizure disorders (1); varicella (1); viral infection (1).